BBS12 (Bardet-Biedl syndrome 12)
Description:
Component of the chaperonin-containing T-complex (TRiC), a molecular chaperone complex that assists the folding of proteins upon ATP hydrolysis. As part of the TRiC complex may play a role in the assembly of BBSome, a complex involved in ciliogenesis regulating transports vesicles to the cilia. Involved in adipogenic differentiation.
Synonyms: C4orf24; FLJ35630; FLJ41559
Tractability: PROTAC: ubiquitination databases record sites on it.
Gene: Protein-coding gene on chromosome 4 (122,732,702 to 122,744,942, forward strand). Ensembl gene ENSG00000181004.
Subcellular location: Cell projection, cilium
Pathways (Reactome):
Organelle biogenesis and maintenance: BBSome-mediated cargo-targeting to cilium
Gene Ontology:
Molecular function: protein binding; ATP binding
Biological process: chaperone-mediated protein complex assembly; negative regulation of fat cell differentiation; photoreceptor cell maintenance
Cellular component: cilium
Genetic constraint (gnomAD): Loss-of-function variants: 8 observed, 10.12 expected, observed/expected ratio (o/e) 0.79, 90% interval 0.46 to 1.42. The upper end of that interval is the gene's LOEUF score, 1.42, which puts it in group 5 of 6, group 1 being the genes least tolerant of losing a copy. Missense variants: 748 observed, 877.11 expected, observed/expected ratio (o/e) 0.85, 90% interval 0.8 to 0.91. Synonymous variants: 308 observed, 325.73 expected, observed/expected ratio (o/e) 0.95, 90% interval 0.86 to 1.04.
Gene-disease validity (ClinGen):
ClinGen rates the evidence that BBS12 causes each of these diseases.
BBS12-related ciliopathy (autosomal recessive): Definitive. Any ciliopathy caused by variants in the BBS12 gene.
Homologues: Orthologues: chimpanzee BBS12 (98% identical), rabbit BBS12 (80% identical), dog BBS12 (79% identical), pig BBS12 (76% identical), guinea pig BBS12 (75% identical), rat Bbs12 (70% identical), mouse Bbs12 (69% identical), tropical clawed frog bbs12 (38% identical), zebrafish bbs12 (31% identical). Paralogues in human: CCT4 (14% identical), PIKFYVE (14% identical), CCT3 (13% identical), CCT7 (13% identical), CCT5 (12% identical), CCT6A (12% identical), MKKS (12% identical), CCT6B (12% identical), TCP1 (12% identical), CCT8L2 (12% identical), CCT8 (11% identical), HSPD1 (10% identical), and 1 more.
Diseases named in the same sentence as BBS12 in open-access papers:
BBS12 is named in the same sentence as 28 diseases in open-access papers, as found by Europe PMC text mining. Sharing a sentence is not in itself a finding about the gene and the disease. The quoted sentences say what the papers report.
Bardet-Biedl syndrome (13 papers, 2012 to 2025). A ciliopathy with multisystem involvement. "It is interesting to point out that mutations in BBS12 gene are responsible for approximately 8% of all cases of Bardet Biedl syndrome reported in the literature." (PMID 37469681, 2023). "For example, HES2, MAFB, RPS12, RPL12, RPS15, and AFF2 are all associated with cancer, whereas BBS12 is a gene related to Bardet-Biedl Syndrome, a multi-organ genetic disease that can involve hypoplasia of the uterus, ovaries, and fallopian tubes." (PMID 34215221, 2021). "The set of genes associated with Bardet-Biedl syndrome is represented in cluster A by the nodes BBS12, BBS10, and BBS7." (PMID 33805313, 2021). "These variations were present in genes BBS12, STIL, COG6 and PIEZO1.A mutation in BBS12 causes Bardet-Biedl syndrome 12 (OMIM #615989)." (PMID 33772059, 2021). "BBS12, a Bardet–Biedl syndrome gene, is required for primary cilia formation and function; ciliary dysfunction could disturb ocular surface homeostasis and immune signaling." (PMID 41476961, 2025). "In Group II, MKKS causes the McKusick-Kaufman syndrome characterized by genitourinary malformations (MIM#236700), and BBS10, and BBS12 Bardet-Biedl syndromes (BBS) type 10 (MIM # 615987) and 12 (MIM # 615989)." (PMID 33076433, 2020). "In Bardet–Biedl syndrome, TTC8, BBS9, WDPCP, and IFT27 were shared by the two pipelines, and BBS4, BBS7, BBS12, and IFT74 suffered significantly different selective pressures between TG and BG birds." (PMID 35456484, 2022).
Obesity (5 papers, 2019 to 2025). Accumulation of substantial excess body fat. "Bbs2, Bbs4, Bbs6, and Bbs12 KOs, as well as a Bbs1M390R/M390R knock-in animals, develop obesity driven by hyperphagia." (PMID 35653384, 2022). "BBS12 is also involved in adipogenic pathways, pointing out to the obesity issue that is a major feature in BBS-patients." (PMID 31888296, 2019). "Thus, the Bbs12-/- mouse model (BBS12; a chaperone protein required for ciliogenesis during adipogenic differentiation of human mesenchymal cells) showed increased obesity, normal glucose tolerance and increased insulin sensitivity in the fat, recapitulating clinical features of BBS." (PMID 35832432, 2022). "Mice that lack the BBS chaperonin-complex protein BBS12 also develop obesity but expand the adipose tissue by hyperplasia and retain normal glucose tolerance and insulin sensitivity." (PMID 40836034, 2025).
breast carcinoma (1 paper, 2020). "The treatment with CyA restored the abundance of 3 proteins at 1% oxygen to a level similar to that in cells grown at 19% oxygen, selenocysteine-specific elongation factor (EEFSEC), Bardet-Biedl syndrome 12 protein (BBS12) and breast cancer anti-estrogen resistance protein 3 (BCAR3)." (PMID 32183695, 2020).
cone dystrophy (1 paper, 2022). An inherited ocular disorder characterized by the loss of cone cells, the photoreceptors responsible for both central and color vision. "Of interest is that the fundus images of patients BBS44-I (BBS3) and BBS58 (BBS12) show evidence of cone dystrophy." (PMID 35886001, 2022).
cone-rod dystrophy (1 paper, 2022). Inherited retinal dystrophies that belong to the group of pigmentary retinopathies. "A total of 16 patients (26%) were found to have a cone or cone-rod dystrophy, but it appears to be distributed evenly between BBS subtypes (3/15 BBS1, 2/3 BBS2, 3/3 BBS3, 1/5 BBS9, 5/20 BBS10, and 2/3 BBS12)." (PMID 35886001, 2022).
hypogonadism (1 paper, 2019). A disorder characterized by decreased function of the gonads. "Patients with renal anomalies should therefore be screened mainly in BBS10, BBS12, BBS6 and those with hypogonadism for variants in BBSome genes." (PMID 31196119, 2019).
kidney failure (1 paper, 2019). An acute or chronic condition that is characterized by the inability of the kidneys to adequately filter the blood. "Clinicians should also closely monitor patients harbouring mutations in BBS10, BBS12, BBS6 to favour early detection of those with renal anomalies, at risk of kidney failure and sudden death." (PMID 31196119, 2019).
Leber congenital amaurosis (1 paper, 2010). Leber congenital amaurosis (LCA) is a retinal dystrophy defined by blindness and responses to electrophysiological stimulation (Ganzfeld electroretinogram (ERG)) below threshold, associated with severe visual impairment within the first year of life. "This strategy has been performed in BBS consanguineous families to detect new genes, such as BBS9, BBS11, and BBS12; in other retinal pathologies, such as Leber congenital amaurosis, this strategy allowed the identification of novel mutations in the LCA5 gene." (PMID 20142850, 2010).
kidney disease (4 papers, 2022 to 2025). "Kidney disease has been described as more prevalent in BBS2-, BBS7-, and BBS9-related BBS, as well as in BBS6-, BBS10-, and BBS12-related BBS." (PMID 40087798, 2025).
cancer (3 papers, 2018 to 2025). A tumor composed of atypical neoplastic, often pleomorphic cells that invade other tissues. "Among the 208 confirmed genes, mutations in NUP37, C18orf8, and BBS12 were detected in 2 cancer tissues." (PMID 30375428, 2018). "These modules contained several cancer regulators such as Intraflagellar Transport (IFT) complex proteins (IFT74, IFT88), BBSome complex proteins (BBS2, BBS7, BBS9, BBS12), exocyst complex components (EXOC3, EXOC4, EXOC6B, EXOC7, and EXOC8), TTC8, TTC21B, EVC, and NEK1." (PMID 40700427, 2025).
BBS12 also shares sentences with these, for which no sentence is quoted: ciliopathy (3 papers); genetic disease (2); retinal degeneration (2); Usher syndrome (2); Alport syndrome (1); arterial hypertension (1); Ataxia (1); Bardet-Biedl syndrome 12 (1); central obesity (1); Glucose intolerance (1); homocysteinemia (1); hyperlipidemia (1); Liver fibrosis (1); Lowe syndrome (1); Methylmalonic aciduria (1); renal dysplasia (1); retinal ciliopathy (1); Retinal dystrophy (1).